CXCR4 (C-X-C motif chemokine receptor 4)
Diseases named in the same sentence as CXCR4 in open-access papers (continued):
Sharing a sentence is not in itself a finding about the gene and the disease.
infection (continued). "Alternatively, homing of MuV-specific T cells to the bone marrow may have occurred between the two timepoints at 1.5 and 9 months post-infection, which would also explain the increased levels of CXCR4 expression at 9 months post-infection." (PMID 34960178, 2021). "Cxcr4 is a known regulator of remyelination in other models of infection and CNS inflammation." (PMID 33816350, 2021). "This suggests that targeting CXCR4 may be particularly beneficial for patients in the later stages of infection." (PMID 34429135, 2021). "Though these interactions may have some role in virus association with specific cells, CD4 and the co-receptor molecules CCR5 and CXCR4 remain the key receptors involved in viral fusion and cellular infection." (PMID 31863725, 2020). "CB2 agonist have been shown to decrease CXCR4-activation-mediated G-protein activity and MAPK phosphorylation, alter the cytoskeletal architecture of resting CD4+ T and impair productive infection following cell-free or cell-associated viral acquisition of CXCR4-tropic HIV-1 in resting cells." (PMID 32471272, 2020). "In contrast, infection by CXCR4-using HXB2 and dual-tropic 89.6 was completely inhibited." (PMID 32762760, 2020). "Furthermore, CCR5 and CXCR4, the receptors for HIV infection, are expressed at the surface CD34+CD133+ HSPCs from umbilical cord blood and that CXCR4 was necessary for the infection by HIV-1." (PMID 33102251, 2020). "In contrast, coreceptor switching to CXCR4 occurs less frequently in subtype C (C-HIV) infections." (PMID 32762760, 2020). "However, in 50% of untreated subtype B infections, CXCR4-using viruses can emerge either exclusively or with CCR5-using viruses." (PMID 32762760, 2020). "In addition, it was indicated that all cells reduced CCR5 and CXCR4 expression, besides becoming resistant to the infection by tropic viruses R5 and X4, even when using double-tropism virus." (PMID 31531340, 2019). "PX-12 also affects oxidoreductase activity and we therefor decided to test if PX-12 interferes with the early infection event by utilizing an infectivity assay consisting of TZM-bl (HeLa/CD4/CXCR4/CCR5) cells which contain a luciferase gene that is under the control of the HIV-1 promoter." (PMID 30948772, 2019). "Our findings are in line with a previous study showing that differences between CCR5-tropic strains and CXCR4 strains in productive infection of MDM occurred during the early stages of HIV-1 life cycle and in particles at levels of reverse transcription and nuclear translocation of viral genomes." (PMID 31234437, 2019). "The role of p38 has been elucidated in the setting of infection of T cells by CXCR4-tropic strains." (PMID 31234437, 2019). "Indeed, rapid decline of CD4 counts and disease progression has also been reported when infection is initiated by dual CCR5/CXCR4 dual-tropic or CXCR4-tropic HIV strains." (PMID 30761146, 2019). "The proportion of infections with CXCR4-using strains investigated among patients with early infection stages, suggesting transmission of X4 variants, ranged from 3% to 26% depending on the population examined and method used to assess viral coreceptor tropism." (PMID 30899060, 2019). "Indeed, CXCR4-using virus is generally understood to be at a disadvantage relative to R5 virus in infected persons; CXCR4-using virus is rarely transmitted, but is usually observed only late in infection and then only in a proportion of individuals." (PMID 30586365, 2018). "In a parallel experiment, the cells were collected to examine the level of gag mRNA, and the qPCR result showed that the copy number of HIV-1NL4-3 significantly decreased 5 days post-infection in the cells expressing CXCR4 mutant P191A compared to wild-type cells." (PMID 29872154, 2018).
infection (continued). "A study carried out at the University of Louisville provided clear evidence of transferring C-X-C chemokine receptor type 4 (CXCR4) by PMVs to CD4+/CXCR4−null cells and, in consequence, making them susceptible to infection by human immunodeficiency virus (X4-HIV)." (PMID 30619239, 2018). "CXCR4 was first found to mediate CD4-independent infection by HIV-2 in 1996." (PMID 29581828, 2018). "In this way, CXCL12 might inhibit CXCR4-tropic infection of memory CD4+ T cells and further inhibit the establishment of HIV latency." (PMID 29085362, 2017). "Because the US27 protein is also present in the virion it is possible that the viral GPCR may have immediate effects on cell signaling after virus entry and influence CXCR4 at an early stage of infection." (PMID 28207860, 2017). "We next tested the effect of the CXCR4 gene disruption on X4-tropic HIV-1NL4-3 infection." (PMID 29141633, 2017). "Next, we assessed whether the editing of the CXCR4 could render cells resistant to replication-competent HIV-1NL4-3 infection." (PMID 29141633, 2017). "Future studies are necessary to examine the impact of US27 on CXCR4 during infection in various cell types to determine whether US27 actually promotes increased migration of infected cells towards CXCL12." (PMID 28207860, 2017). "During infection, potentiation of CXCR4 signaling by US27 might promote increased migration of infected cells towards CXCL12-expressing tissues, such as the bone marrow." (PMID 28207860, 2017). "FIV infection of the nervous system shares many common features with HIV infection including usage of the co-receptor, CXCR4, similar cellular targets, rapid penetration and infection of the CNS, the generation of a diffuse CNS inflammatory response and gradual, progressive pathogenesis." (PMID 29056673, 2017). "CXCR4 engagement also promotes the migration of neutrophils from inflamed skin into draining lymph nodes, a process thought to participate in the control of pathogens through initiation of immune responses or conversely in the spreading of infection." (PMID 27111140, 2016). "At week 1 post infection CXCR4, FAS and PTPN22 showed higher expression in line L10H." (PMID 26819139, 2016). "In the present study, we expanded our previous work by determining the prevalence of CXCR4-using viruses in MPS data from a total of 84 Brazilian first-time blood donors consisting of 63 subjects with LS infection and 21 with unknown stage information." (PMID 26862570, 2016). "Indeed, the parasitic success in Cxcr4+/1013 mice was normalized either upon depleting neutrophils, including the pool in the skin, or bypassing the skin via the intravenous infection of L3." (PMID 27111140, 2016). "Time course analysis of the circulating neutrophils counts in Cxcr4+/1013 mice throughout subcutaneous (SC) infection of L3 revealed an increase, which tended to normalize the circulating neutrophil counts from 20 days followed by a progressive decay back to initial levels at day 70 p.i.." (PMID 27111140, 2016). "Furthermore, naïve Tregs are capable of upregulating the membrane expression of CXCR4 and CCR5 upon TCR stimulation, increasing their susceptibility to infection." (PMID 27242797, 2016). "Therefore, like most dual-tropic viruses, R3A relies more heavily on CXCR4 than CCR5 usage for infection in primary PBMC." (PMID 27026376, 2016). "C34-conjugated CCR5 and CXCR4 were unable to be used for infection by R5- and X4-tropic viruses, respectively, and exhibited potent inhibition over unconjugated receptors with inhibition at input ratios of expression plasmids as low as 1 C34-conjugated to 10 unconjugated receptors." (PMID 27855210, 2016). "In the original studies, Nef, a 27–34 kD myristoylated protein expressed early in the infection cycle in host cells, was shown to compete with stromal cell-derived factor 1-alpha (SDF-1α) a natural ligand of CXC chemokine receptor 4 (CXCR4), and induce apoptosis during the infection." (PMID 26318034, 2015).
infection (continued). "However, in vivo, CCR5 and CXCR4 are the major co-receptors supporting the infection, and HIV-1 uses either one or both co-receptors for entry." (PMID 29061947, 2015). "Although HIV-1 subtype C strains (C-HIV) account for the majority of HIV-1 infections worldwide, the susceptibility of CD4+ memory T-cells to infection by CCR5- (R5) and CXCR4-using (X4) C-HIV is unknown." (PMID 25387392, 2014). "However, a recent data has demonstrated CXCR4-tropic viruses in early-diagnosed infection, increasing the possibility of using CXCR4 in early viral transmission." (PMID 24980635, 2014). "In contrast, both CCR5 and CXCR4 supported infection by the majority of isolates tested." (PMID 24980635, 2014). "It is known that SupT1 cells are CXCR4-expressing cells and susceptible to infection by X4-tropic, but not by R5-tropic HIV-1 strains." (PMID 24714696, 2014). "These mutations did not confer CXCR4-using ability, and the infection-competent pseudoviruses were still CCR5-tropic." (PMID 24676404, 2014). "Accordingly to their phenotype naïve Treg were more susceptible to in vitro infection when CXCR4-tropic strain (HIV-1 IIIB) was used rather than CCR5-tropic strain using HIV-1 BaL." (PMID 23908654, 2013). "We observed similar results in infection assays performed with both CXCR4-tropic (IIIB) and CCR5-tropic (BaL) HIV-1 isolates, with the all-β, alternatively-folded conformation (W55D) conferring inhibition, and the chemokine-folded conformation (CC3) showing minimal, if any, activity." (PMID 24385911, 2013). "Together, our results, which reflect the natural history of C-HIV from chronic to advanced stages of infection, suggest that C-HIV pathogenesis is indeed driven principally by R5 viral strains, with functionally-relevant CXCR4-using variants detected very infrequently in our cohort." (PMID 23824043, 2013). "Interestingly, despite the CXCR4 signalling pathway was highlighted for both HP and LP infection when compared to mock-infected samples, it was also the signalling pathway that discriminated the HP and LP infections when compared to each other." (PMID 24015922, 2013). "Thus the ability of Prostratin to inhibit productive infection with FIV cannot be explained by the down-regulation of expression of either CD134 or CXCR4." (PMID 23201205, 2013). "Infection with CXCR4-using (CXCR4 or DM) virus precludes therapeutic benefit from CCR5-antagonist." (PMID 23421710, 2013). "ZFNs that can disrupt the CXCR4 gene in CD4+ T-cells have also been developed and it has been demonstrated that they confer resistance to cells against the X4-tropic HIV-1 strains associated with late-stage infection." (PMID 23364195, 2013). "Mucosal LCs likely prevent CXCR4 using viruses from establishing a new infection." (PMID 24369910, 2013). "The CXCR4-tropic SHIV-infection in pigtail macaques may also represent a less relevant model for most acute HIV infections in humans, where natural transmission is largely restricted to CCR5-tropic viruses." (PMID 23460840, 2013). "FDCs also increase the T-cell expression of the HIV coreceptor CXCR4 and these cells become highly susceptible to infection with small quantities of virus that do not infect other cells with lower levels of CXCR4." (PMID 23049531, 2012). "In addition, CXCR4-tropic (X4) virus HIV-1NL4-3 strongly depleted the central memory CD4+ T cell subset in the hNOK/B51Tg mice after an infection with HIV-1." (PMID 22880104, 2012). "Their lack of susceptibility to productive infection with CXCR4-utilizing HIV-1 strains further emphasizes the importance of when, relative to CCR5 or CXCR4 expression, the monocytoid cell is cycling." (PMID 22911696, 2012). "To test this hypothesis, we examined the effect of cannabinoid receptor activation on HIV viral transmission and productive infection in CD4+ T cells using a GFP-expressing, CXCR4-tropic HIV-1 variant." (PMID 22448282, 2012).
infection (continued). "In this study, we show that intranasal (i.n.)infection of mice with a fully virulent Y. pestis strain is sensed early by the BM compartment, resulting in a reduction in CXCR4 levels on BM neutrophils and their subsequent release into the blood 12 hours (h) post infection." (PMID 23189271, 2012). "Thus, modification of the CXCL12/CXCR4 axis grants control over the pathology's development in these infection models." (PMID 22511975, 2012). "Experiments in which we examined CCR5 and CXCR4 expression on CD4T recovered from cultures of infected and uninfected primary macrophages demonstrated profound loss of CCR5+ CD4T in the presence of infection." (PMID 22911696, 2012). "The goal of this study was to determine whether host factors such as the chemokine axis CXCL12/CXCR4, which notably participates in the control of immune surveillance, can influence the outcome of the infection." (PMID 22511975, 2012). "Thus, the small amount of CXCR4-dependent infection seen in NP2/CD4/CXCR4 cells is likely due to the over-expression of this coreceptor and does not reflect CXCR4 use on primary cells." (PMID 22693444, 2012). "The challenge viruses used in these assays were selected for growth in CrFK cells and, during this process of CrFK-adaptation, viruses were adapted to CD134-independent infection mediated by a direct interaction with CXCR4 (analogous to CD4-independent infection with HIV)." (PMID 22069520, 2011). "CD4/CXCR4 clustering was dependent on actin polymerization and is required for entry and infection." (PMID 21994805, 2011). "In contrast to HIV-1, however, CXCR4 usage by SIVs in models of nonpathogenic and pathogenic infection is rarely observed." (PMID 21284906, 2011). "Indeed, monophyletic exclusively CXCR4-using variants were detected in plasma and archived in PBMC of two patients (D and E) soon after infection with both genotypic and phenotypic techniques (SVMgeno2pheno algorithm and genotypic rule; and phenotypic assay)." (PMID 21887243, 2011). "We first show that there is a threshold level of preservation of CD4+ T cells and a threshold viral load in the acute phase that correspond to the chronic phase thresholds of prolonged survival (for longer than 600 days) in CXCR4-tropic SHIV89.6P infection in rhesus macaques." (PMID 21359149, 2011). "Tonsil lymphoid cells have an increased susceptibility to infection with HIV-1 compared to PBMC, which may in part by ascribed to the increased expression of the viral co-receptor CXCR4." (PMID 21284900, 2011). "This phenotype among X4 variants is also linked, at least in part, to the ability of some X4 strains to use CXCR4 at the low levels expressed on macrophages, as CXCR4 overexpression can in some cases render macrophages permissive for infection by X4 prototypes." (PMID 21284902, 2011). "This may result from a lack of transmission or to the inability of recently transmitted CXCR4-using virus to compete with co-existing R5 HIV-1 during the earliest phase of infection." (PMID 21284904, 2011). "The present study is the first report that documents the unique property of an anti-humanCXCR4 mAb (clone A120) which upon ligation of CXCR4 via the ECL1/ECL2 domains strongly blocks the infection of not only X4 but also R5 and dual tropic HIV-1 strains in freshly in vitro activated PBMC cultures." (PMID 22018245, 2011). "Given the low sensitivity of variants B14 and B28 to antagonism by sFc-CD134 on IL2-dependent (MYA-1) T cells, we postulated that these variants may partially escape antagonism by sFc-CD134 by utilising CXCR4 for infection." (PMID 20420700, 2010). "In our studies, levels of downregulation of Nef-mediated CXCR4 derived from unintegrated DNA correlated well with results obtained in productive infection and are also in agreement with the finding that such downregulation occurs to a lesser extent than is seen for CD4." (PMID 20465832, 2010).
infection (continued). "Moreover, it has been shown that HIV-1 subtype D has a preference for CXCR4 tropism early in infection, and a connection with the faster disease progression seen in this subtype has been suggested." (PMID 20307309, 2010). "Recombinant HIV-1 viruses of B and C subtypes comprising the pol fragments encoding protease, integrase and either the whole RT or a chimeric RT from different isolates of the C and B subtypes, were used for infection of cells expressing CXCR4 or CCR5 co-receptors." (PMID 20939905, 2010). "However, CD4-expression alone is insufficient to confer susceptibility to infection with HIV, which also requires co-receptors, principally the chemokine receptors CXCR4 and CCR5." (PMID 20420700, 2010). "Given that FIV uses a single co-receptor (CXCR4) for infection, the observation that the interaction between the virus and its primary receptor evolves in vivo may provide a mechanism whereby the virus can expand into additional cellular compartments." (PMID 20420700, 2010). "CCR5 is undoubtedly the main HIV coreceptor, involved in virus entry and cell-to-cell spread: Such R5-tropic viruses are nearly always involved in the initial infection, while HIV strains using the CXCR4 coreceptor are observed only seldomly in the early infection." (PMID 21994649, 2010). "Infection of NP2/CD4/CXCR4 cells is 35X (MCN) and 160X (MCR) greater than on HeLa/CD4 cells." (PMID 20929586, 2010). "In addition, it has been reported that the second extracellular loop of CXCR4 contains a critical determinant for the function of CXCR4 as a receptor for infection with FIV." (PMID 20502526, 2010). "HIV-1 co-receptor usage is associated with viral tropism, pathogenesis, and disease progression because viruses that utilize CCR5 (R5) initiate infections, while viruses that use CXCR4 (X4) emerge later in HIV-1 infected individuals to herald accelerated disease progression." (PMID 19442296, 2009). "Within 48 hour after infection of CD4+CXCR4+ HeLa cells with the syncytium-inducing HIV-1LAI strain, a significant fraction of cells, preferentially syncytia, exhibited mitochondrial cytochrome c release, caspase-3 activation and apoptotic chromatin condensation." (PMID 18560558, 2008). "However, towards the later stages of the infection, nearly half of subtype B strains switch their coreceptor usage to CXCR4 (X4 strains)." (PMID 18328091, 2008). "In fact, CD34+ HPCs have been shown to secrete the CCR5 ligands MIP-1α, MIP-1β, and RANTES, and the CXCR4 ligand SDF-1, which may compete with infectious HIV-1, either CCR5- or CXCR4-utilizing virus, and consequently block infection." (PMID 19112504, 2008). "Alteration in CXCR4 expression after infection by HIV-1 could result from sequestration of CXCR4 intracellularly or from the direct effects of other HIV-1 proteins on the synthesis of CXCR4 or its transport to the cell surface." (PMID 18190699, 2008). "NP-2/CD4/CXCR4 cells were highly susceptible to all HIV-1 strains, except the Ba-L and SF162 strains, when tested on day 6 after infection, while NP-2/CD4/CCR5 cells were highly susceptible to five HIV-1 strains, Ba-L, GUN-1WT, GUN-4WT, GUN-7WT, and SF162, but not to the IIIB strain." (PMID 18577234, 2008). "Thus, we chose the emergence of CXCR4-using viruses atd = 50 from thiscalibration since usually X4 viruses appear at later stages of infection." (PMID 19079613, 2008). "NP-2/CD4/CXCR4 cells showed a high susceptibility to AG204, AG206, AG208, HCM303, HC305, HCM308, and HCM309 isolate, while less than 1% of HIV-1 antigen-positive cells were detected after infection with HCM342, mIDU101, or mSTD104 isolates." (PMID 18577234, 2008). "Nevertheless, SDF-1 has been shown to regulate adhesion survival and proliferation of HPCs, and its role in the HIV-1-infected BM warrants investigation, as it may be involved in limiting infection by CXCR4-utilizing strains of HIV-1." (PMID 19112504, 2008).